S100B (S100 calcium binding protein B)
Diseases named in the same sentence as S100B in open-access papers (continued):
Sharing a sentence is not in itself a finding about the gene and the disease.
mood disorder (continued). "Numerous studies have shown that S100B is altered in both serum and CSF of patients with mood disorders." (PMID 27931233, 2016). "Meta-analysis (193 mood disorder, 132 healthy controls) confirmed elevated serum and CSF S100B levels in mood disorders, particularly during acute depressive episodes and mania." (PMID 23547920, 2013). "If mood disorders are ultimately glial disorders as suggested by Rajkowska, one would expect elevated serum levels of S100B paralleled by unaltered neuronal marker protein NSE." (PMID 20585358, 2010). "Here, we review studies investigating the glial marker S100B in serum of patients with mood disorders." (PMID 20585358, 2010). "To better evaluate the relevance of S100B in mood disorders, we recently conducted a systematic, quantitative meta-analysis using MedLine and Current Contents search engines (search strategy: [S100 OR S-100] AND [depression OR mania])." (PMID 20585358, 2010). "We measured levels of S100B in serum of 40 adolescents with acute psychosis, 24 adolescents with mood disorders and 20 healthy controls." (PMID 20559426, 2010). "The main finding of our study is that S100B is a biomarker that can help predict suicidality in adolescent patients with psychosis and mood disorders." (PMID 20559426, 2010). "However, we did find a significant causal effect of S100B on the other mood disorder, BIP: a one SD increase in S100B levels increased the odds ratio of BIP by 1.07 (95%CI: 1.03–1.13; p = 0.002)." (PMID 37225692, 2023). "In support of this hypothesis, studies consistently show that S100B is elevated in mood disorders, more evidently in MDD than in BD." (PMID 35448545, 2022). "Clinical studies in adult patients indicate that S100B is elevated in mood disorders and might be a potential biomarker for mood disorders and successful antidepressive treatment." (PMID 34099858, 2021). "Mood disorder patients have increased S100B levels, and serum concentration of S100B may be a possible predictor of antidepressant response in patients." (PMID 31231189, 2019). "On the basis of S100B levels in the lumbar cerebrospinal fluid of depressive patients, ventricular CSF levels have been estimated, strongly indicating that, in mood disorders extracellular S100B levels in the brain are in the nanomolar range far below micromolar concentrations." (PMID 26364276, 2015). "Increased serum levels of S100B may indicate glial alterations in mood disorders either due to brain damage or due to functional secretion of S100B by astrocytes and/or oligodendrocytes." (PMID 20585358, 2010). "In sum, results support the hypothesis that S100B is involved in the pathogenesis of mood disorders, particularly MDD." (PMID 20585358, 2010). "Additionally, we compared results of the meta-analysis for mood disorders with another recent meta-analysis investigating serum S100B with the same method in 420 patients with schizophrenia." (PMID 20585358, 2010). "In a combined clinical study and a meta-analysis of published studies on S100B involving 193 patients suffering from mood disorders and 132 healthy controls, the authors concluded that serum levels of S100B are consistently elevated during acute major depressive or manic episodes." (PMID 19936105, 2009). "Thus, both datasets pointed to a causal effect of increased blood S100B levels on the lifetime risk of mood disorders, but not on neurodevelopmental or neurodegenerative disorders." (PMID 37225692, 2023). "Hence, it has been proposed that S100B serum and CSF levels may represent a suitable surrogate marker of glial damage or dysfunction in mood disorders." (PMID 27931233, 2016). "One might therefore conclude that brain damage is not the primary cause of elevated S100B in mood disorders." (PMID 20585358, 2010).
mood disorder (continued). "To validate the histopathologically generated hypothesis that mood disorders are characterized by specific glial pathology in vivo, we recently measured S100B simultaneously with neuron-specific enolase (NSE) in the serum of patients with MDD and healthy age- and gender-matched control subjects." (PMID 20585358, 2010). "Mean serum levels of S100B as reported in our and other studies of mood disorders do not reach this threshold." (PMID 20585358, 2010). "Serum S100B levels were significantly higher (p<0.05) and correlated to severity of suicidal ideation in patients with psychosis or mood disorders, independent of psychiatric diagnosis." (PMID 20559426, 2010). "By indicating glial alterations without neuronal changes, serum S100B studies confirm specific glial pathology in mood disorders in vivo." (PMID 20585358, 2010). "Previous studies have shown that S100B, which is found in astro- and oligodendroglia, but not in microglia in the human brain, is altered in both serum and cerebrospinal fluid in mood disorders." (PMID 20585358, 2010).
bipolar disorder (21 papers, 2010 to 2025). A disorder of the brain that causes unusual shifts in mood, energy, activity levels and the ability to carry out day-to-day tasks. "There is scarce evidence regarding a possible association between the calcium-binding protein S100B and impaired cognition in bipolar disorder." (PMID 38227084, 2024). "Calcium binding protein S100B is a measure of accumulated oxidative stress, and its level in individuals with bipolar depression is approximately two-fold higher compared to healthy subjects." (PMID 37386057, 2023). "An interesting issue worth pursuing in future research is diagnosis change from unipolar to bipolar affective disorder in youths and its correlation with the S100B serum." (PMID 34099858, 2021). "In these participants, S100B levels correlated with cytochrome c release, a mitochondrial apoptotic marker, supporting the oxidative stress/mitochondrial dysfunction interplay in bipolar depression." (PMID 37386057, 2023). "The main finding of this study is that the following adipokines correlated with MS in the bipolar depression women group: visfatin, S100B, and leptin had a positive correlation, whereas adiponectin, leptin-receptor, and adiponectin/leptin ratio showed a negative correlation." (PMID 37960185, 2023). "In this study, we showed that in bipolar depression, adipokines correlated with MS in the women group: VIS, S100B, and LEP had a positive correlation, whereas ADIPO, LEP_R, and ADIPO/LEP ratio showed negative correlation." (PMID 37960185, 2023). "However, a recent postmortem analysis showed that the numerical density of S100B-immunopositive astrocytes was bilaterally decreased in the CA1 pyramidal layer of the hippocampus in MDD and bipolar disorder (BD) patients compared to controls." (PMID 27931233, 2016).
Down syndrome (21 papers, 2008 to 2025). "The S100B gene is located in the 21q22 region, a chromosomal locus whose duplication has been associated with the occurrence of Down Syndrome (DS)." (PMID 39027325, 2024). "The S100B gene codes for a calcium binding protein of the S-100 protein family and is located on chromosome 21q22.3 near risk regions for Alzheimer’s disease, bipolar affective disorder, and down syndrome." (PMID 32379790, 2020). "Additionally, S100B has been associated with Down Syndrome, a genetic variation where the most profound neurological features are mental retardation, seizures and early onset AD." (PMID 31156365, 2019). "Levels of S100B are increased in neuronal progenitor cells of patients with Down Syndrome and in human induced pluripotent stem cells derived from Down Syndrome patients." (PMID 31156365, 2019). "Recently, strong expression and release of S100B has been shown for astroglia obtained from human induced pluripotent stem cells derived from Down Syndrome (DS) patients and related with reduced neurogenesis and increased neuronal cell death." (PMID 27159591, 2016). "High levels of S100B released by astrocytes in Down syndrome patients are responsible for reduced neurogenesis of neural progenitor cells and induction of cell death in neurons." (PMID 27159591, 2016). "It is also considered possible that initial events in AD pathogenesis are driven by cytokines, because there occurs inflammation of neurons, glial cells dramatically multiply and over-express IL-1 and S100B in the brains of down syndrome patients." (PMID 27875990, 2016). "These mice were designed to model the elevated S100B that is often a part of the Down syndrome genotype." (PMID 20827311, 2010). "Serum levels of S100B are greatly increased in Down syndrome and postmortem brain studies show lifelong overexpression of the protein." (PMID 20827311, 2010). "S100β was overexpressed in brain tissue of patients with AD and Down syndrome." (PMID 37730895, 2023). "Furthermore, overproduction of S100B contributed to the Aβ-induced neuritic changes in Down’s syndrome." (PMID 31217937, 2019). "Supporting this notion, it has been reported that astrocytic overexpression of S100B drives dystrophic neurite outgrowth, culminating in the formation of neuritic plaques in Down's syndrome, and that S100B induction precedes appearance of neuritic β-amyloid plaques in the PSAPP AD mouse model." (PMID 20862385, 2010). "Moreover, augmented expression of S100B has been reported in the brains of patients with Down's syndrome and in AD." (PMID 20862385, 2010). "Interestingly, Down Syndrome almost inevitably leads to an extremely early development of AD and the increase in S100B is thought to contribute to the pathology of both." (PMID 20827311, 2010). "Similarly, it was suggested that elevated S100B levels are involved in the development of Down's syndrome and AD; its expression was also correlated with the density of dystrophic neuritis with overexpressed AβPP." (PMID 18573219, 2008). "Moreover, within the S100 protein family, it is important to mention that the S100B (encoded by a gene located on the chromosome 21) was shown to be involved in APP processing, protein inclusion formation, and tau post-translational modifications in Down syndrome." (PMID 36394661, 2023).
subarachnoid hemorrhage (21 papers, 2010 to 2024). A serious neurological disorder characterized by intracranial hemorrhage into the subarachnoid space. "Other blood-based biomarkers including the Glial Fibrillary Acidic Protein (GFAP), the Neuron-Specific Enolase (NSE), and the S100b protein have been also evaluated as prognostic factors for patients with traumatic brain injury and subarachnoid hemorrhage." (PMID 39514015, 2024). "S100B is released after brain injury and high levels of S100B can be detected in a variety of pathological injuries to the CNS, such as subarachnoid haemorrhage (SAH), acute brain injury, traumatic brain injury (TBI), and acute ischemic stroke." (PMID 33419282, 2020). "The clinical utility of S100B has been evaluated in various studies, indicating a correlation between increased serum S100B and poorer outcome in traumatic brain injury and subarachnoid hemorrhage." (PMID 24179506, 2013). "Serum concentrations of KLK6 and S100B (ng/mL) in the initial sample and all samples collected within the first 56 hours from patients with subarachnoid hemorrhage." (PMID 23049835, 2012). "The utility of S100B has also been a matter of interest in the context of subarachnoid hemorrhage." (PMID 32575870, 2020). "Later on, S100B was shown to be sensitive enough to detect and assess different traumatic intracranial lesions, including cerebral contusions, subdural hematomas and traumatic subarachnoid hemorrhages, as well as epidural hematomas." (PMID 27957604, 2017). "External ventricular drain placement has also been shown to affect S100B levels, although this time in the CSF, and serum S100B levels greater than 0.7 μg/dL have been observed to correlate with 100% mortality for TBI and subarachnoid hemorrhage." (PMID 34522534, 2021). "Our clinical experience, having followed S100B in close to 3,000 NICU patients (both TBI and subarachnoid hemorrhage patients), is that levels prior to verified brain death are highly variable." (PMID 27957604, 2017).
Insulin resistance (20 papers, 2010 to 2025). Increased resistance towards insulin, that is, diminished effectiveness of insulin in reducing blood glucose levels. "The serum level of S100B correlates with insulin resistance, metabolic risk score, and fat cell size." (PMID 37960185, 2023). "Insulin resistance, a hallmark of prediabetes, contributes to chronic low-grade inflammation and endothelial dysfunction, which can in turn influence levels of circulating biomarkers such as IL-6, D-dimer, and S100B." (PMID 41150802, 2025). "Additionally, serum levels of S100A4, S100A8/S100A9, S100A12, and S100B correlate with insulin resistance/T2D, metabolic risk score, and fat cell size." (PMID 35328627, 2022). "In summary, the decrease in S100B in patients with T2DM may be related to insulin resistance and deficiency." (PMID 32112645, 2020). "Interestingly, insulin resistance in schizophrenic patients may be closely linked to serum S100B changes." (PMID 20672003, 2010). "Prior literatures have demonstrated the relationship between POCD related to S100β and insulin resistance." (PMID 38915348, 2024). "In schizophrenic patients, where blood S100B levels are known to be elevated, they have been shown to be related to insulin resistance and, also, to visceral obesity." (PMID 38255850, 2024). "In support of this observation, rats fed on a ketogenic diet, which exhibits signals of insulin resistance, also demonstrate elevated levels of serum S100B (D Ziegler, unpublished observation)." (PMID 20672003, 2010). "Moreover, the participants of the study had elevated insulin levels, showed high values on the HOMA-IR index of insulin resistance, and the serum level of S100B protein was significantly elevated compared to healthy volunteers." (PMID 34073816, 2021). "Moreover, adipokines (leptin: r = 0.545, P = .001, HGF: r = 0.441, P = .012, resistin: r = 0.377, P = .033) and C-peptide/glucose ratios (an estimate of insulin resistance, r = 0.432, P = .014) predicted S100B levels." (PMID 20631894, 2010). "However, the findings also indicate that lower S100B levels are associated with worse cognitive function, suggesting that while insulin resistance may lead to reduced S100B, the protein could still play a critical role in neuroprotection and cognitive health." (PMID 41150802, 2025). "Our study found that administration of a vitamin-rich carbohydrate beverage (5 ml by gavage) could effectively attenuate postoperative insulin resistance, improve insulin sensitivity, and decrease the production of IL-1β and S-100β in the plasma of elderly rats after splenectomy." (PMID 31092210, 2019). "In addition to insulin resistance, adipose tissue alterations are also observed in bipolar affective disorders and schizophrenic patients, which are accompanied by elevations in serum S100B." (PMID 20672003, 2010). "Fasting plasma glucose, insulin, insulin resistance (HOMA-IR index, IRI), the S-100β protein level, and the inflammatory mediators IL-1β, IL-6 and TNF-α were assessed after surgery (postoperative day (POD) 1 and 3)." (PMID 31092210, 2019). "Patients with long COVID exhibit elevated levels of HAMD, HAMA, and FF scores, as well as increased CRP, PGE2, GAL-GALR1 signaling, insulin resistance, PAI1, NSE, and S100B compared to individuals without long COVID." (PMID 40048451, 2025).
intracranial hemorrhage (18 papers, 2010 to 2023). Bleeding within the SKULL, including hemorrhages in the brain and the three membranes of MENINGES. "They observed that serum S-100B levels, assessed within 24 h of symptom onset, possess an independent association with symptomatic intracranial hemorrhage and symptomatic brain edema in patients with acute ischemic stroke." (PMID 37752283, 2023). "The detection of high S-100β in blood and cerebrospinal fluid contribute to identify progressive intracranial hemorrhage after TBI, which is associated with mortality and poor prognosis." (PMID 35978006, 2022). "Nonetheless, there is evidence that increased levels of S100b in blood of AIS patients are associated with increased intracranial hemorrhage rate following thrombolytic therapy." (PMID 36756347, 2022). "Moreover, serum S100B levels measured within 24 h after symptom onset were independently associated with the development of symptomatic intracranial hemorrhage and symptomatic brain edema in acute ischemic stroke patients." (PMID 37474905, 2023). "It is possible there might be some benefits if urine S100B could be used past the 6-h limit of serum protein S100B but when more than 6 h after trauma have passed, the risk of large brain injury due to intracranial hemorrhage is probably significantly smaller." (PMID 31388712, 2021). "Since then, many observational studies have confirmed the usefulness of measuring blood S100B for the exclusion of an intracranial hemorrhage in mTBI patients." (PMID 37047574, 2023). "In population 1, the serum S100B in the samples drawn 6 h or less from trauma (12/201 patients with intracranial hemorrhage) had the best cutoff at 0.1 μg/l (AUC = 0.589, 95% CI 0.436–0.741, p = 0.304)." (PMID 31388712, 2021). "For the urine S100B samples drawn 6 h or less from trauma (21 samples from patients with intracranial hemorrhage), the AUC was 0.502 (95% CI 0.371–0.633, p = 0.977)." (PMID 31388712, 2021). "In the combined populations 1 and 2, for the serum S100B samples drawn 6 h or less from trauma (23 samples from patients with intracranial hemorrhage), the AUC was 0.628 (95% CI 0.523–0.734, p = 0.044)." (PMID 31388712, 2021). "In population 1, the best cutoff for urine S100B, sampled within 6 h from trauma (10/180 patients with intracranial hemorrhage), was 0.09 μg/l (AUC = 0.635, 95% CI 0.454–0.816, p = 0.151)." (PMID 31388712, 2021). "One patient with intracranial hemorrhage had a serum S100B value of less than the clinical cutoff of 0.10 μg/l, measured within the 6-h limit." (PMID 31388712, 2021). "The median levels of S100B taken within 6 h from population 2 with intracranial hemorrhage are higher, and the median levels of the urine samples are lower in population 2 than in population." (PMID 31388712, 2021). "Patients who were admitted for intracranial hemorrhage were sampled for 48 h to assess S100B-level, renal function, urine-pH, etc." (PMID 31388712, 2021). "The analysis of the temporal profile of the serum and the urine S100B levels of patients with intracranial hemorrhage shows that both levels drop fast within the first 6 h." (PMID 31388712, 2021). "The difference in the median serum S100B in these 11 samples from population 2, compared with the 13 patients with intracranial hemorrhage in population 1, was 0.22–0.18 μg/l = 0.04 μg/l (p = 0.794)." (PMID 31388712, 2021). "This study cannot support ruling out intracranial hemorrhage with urine S100B." (PMID 31388712, 2021). "If the cutoff for ruling out intracranial hemorrhage in urine would be established at a very low level of urine S100B, this higher CV might be a problem." (PMID 31388712, 2021). "S100B levels were markedly increased following the development of intracranial hemorrhage." (PMID 31156541, 2019).